PARP1 (poly(ADP-ribose) polymerase 1)
Diseases named in the same sentence as PARP1 in open-access papers (continued):
Sharing a sentence is not in itself a finding about the gene and the disease.
cancer (continued). "However, the cytotoxic effect of PARP1 inhibitors against cancer cells is mostly mediated by the trapping of PARP1 at sites of DNA damage that generates stalled replication forks during the S phase of the cell cycle." (PMID 36743979, 2023). "Proteins such as BRCA1, BRCA2, PALB2, ATM, CHEK1, CHEK2, and RAD51 are involved in the HR repair process, while poly(ADP-ribose) polymerases 1 and 2, referred to as PARP1 and PARP2, are associated with the BER, with some of these proteins being frequently mutated in cancer patients." (PMID 38004468, 2023). "PARP1 is necessary for genomic stability, suggesting that its inhibition should derive genomic instability, which is one of the principal hallmarks of aging as well as of cancer." (PMID 36743979, 2023). "ETV also appears to inhibit PARP-1, has a high genetic barrier, reducing the chance of resistance development, and can also prevent the reactivation of the hepatitis B virus in cancer patients, which have proven to be significant advantages regarding its use as a repurposed drug in oncology." (PMID 38004468, 2023). "As many as twenty-two compounds target PARP1 according to DrugBank, among which its inhibitors olaparib, rucaparib, niraparib, and talazoparib have been approved or are under development for treatment of various cancers." (PMID 37108815, 2023). "The phenomenon was explored on a molecular level: when exposed to cisplatin, cancer cells balance available NAD+ between PARP-1 (PARP-1 activity is needed for DNA repair) and PHGDH in favor of the repairing mechanism mediated by PARP1 and, instead of activating SSP, take serine from the medium." (PMID 37376060, 2023). "The significant increase in sensitivity of ALL cells to PARP1/2 inhibitors relative to non-cancer cells indicates that this may be a potential pan-ALL therapeutic target that was discovered through protein abundance analysis." (PMID 37989729, 2023). "Small nucleolar RNAs (snoRNAs) were also reported as important DNA damage-independent activators of PARP-1 activity in the control of ribosome biogenesis, a pathway that may contribute to the effectiveness of PARPi in the treatment of a number of cancer types." (PMID 37609662, 2023). "Our in vivo data further support the exciting possibility that by inducing potent PARP1 trapping, nimbolide potentially could be useful as a previously unknown class of PARP1-targeting agents for the treatment of BRCAmut cancers." (PMID 37878693, 2023). "The pan-cancer analysis has shown that higher PARP1 expression is present in 27 tumor tissues." (PMID 36750717, 2023). "Thus, ETS transcription factors promote both PARP-1 expression and activity to allow cancer cells to improve the efficiency of DNA repair and overcome genotoxic stress." (PMID 37686260, 2023). "A potential cancer therapy involves targeting the DNA repair process by inhibiting PARP-1." (PMID 36814851, 2023). "PARP1 is found to be linked with the mechanisms relating to proapoptotic mechanisms and overexpression might be due to defective cleavage of PARP1 and reduced apoptosis hence long survival of cancer cells." (PMID 36809279, 2023). "Hence, high-LET alpha and Auger-emitting PARP-1 inhibitors targeting cancer cells should have even greater therapeutic efficacy." (PMID 36834491, 2023). "Yet, PARP-1 inhibition impressively increases this ETS-dependent formation of DSB in cancer cells." (PMID 37686260, 2023). "The combined causes of ATP depletion, due to mitochondrial impaired activity on one hand, and deregulated nuclear activity of PARP-1 on the other hand, converge to evoke deregulated, ongoing autophagy which results in the onset of necrotic death in Fer/FerT targeted cancer cells." (PMID 36982326, 2023). "Similarly, inhibitors of poly (ADP-ribose) polymerase-1 (PARP1), an enzyme that plays an important role in the DNA damage response, have been developed as therapeutic anti-cancer agents." (PMID 37566008, 2023).
cancer (continued). "Cancer cells exhibiting DNA fragmentation, changes in expression of several apoptotic proteins such as Bcl2, cytochrome-c and formation of cleaved products of caspase 3 and PARP-1 suggests ellagic acid induces cell death via mitochondrial pathway of apoptosis." (PMID 37256897, 2023). "Therefore, novel PARP1 inhibitors with increased trapping capacity are promising candidates to target cancer cell death." (PMID 36743979, 2023). "In conclusion, we and others have provided evidence that ETS transcription factors may be potential new candidates for biomarkers of cancer cell sensitivity to PARP-1 inhibition." (PMID 37686260, 2023). "Additionally, keeping in mind that patients’ harboring BRCA1/2 or HRR mutations are benefitted from conventional PARP-1 inhibitors, PARP-1 Auger therapy has the advantage that its use can be extended beyond BRCA1/2 defective cancers." (PMID 36834491, 2023). "PARP1 regulates chemokine signalling, facilitating tumour dissemination at several key steps of metastasis, including angiogenesis, adherence of tumour cells to endothelium, cell migration, and cancer cell extravasation at the metastatic site." (PMID 36941406, 2023). "On the other hand, PARP-1 depletion also leads to dysfunctional DNA repair machinery, severe DNA damage, and consequently promoting cell death, which has been used as the strategy in cancer treatment." (PMID 37405135, 2023). "This combination upregulates AIF, BBC3, PARP1, and Caspase‐3 genes in cancer cells to >25‐fold." (PMID 36241419, 2023). "Furthermore, these studies demonstrated that pharmacological inhibition of PARP-1 specifically sensitises ETS-expressing cancer cells to DNA damage and limits tumour progression." (PMID 37686260, 2023). "In addition to ADP-ribosylation systems implicated in bacterial or viral infections, the primary connection between ADP-ribosylation and human health comes from sensitivity of some cancer phenotypes to the inhibition of PARP1 and PARP2." (PMID 37832523, 2023). "This indicate that PARP-1 could have different roles depending on the type of cancer, or even that, PARP-1 function could be highly influenced by the heterogeneity context." (PMID 36902215, 2023). "Thus, the PRMT6/PARP1/CRL4B complex maintains carcinoma progression by reducing the amplitude of circadian rhythms and circadian oscillations." (PMID 36941223, 2023). "These cancer cells utilize other DDR systems including PARP1." (PMID 35801078, 2022). "Moreover, our IF staining showed that the expression of both cleaved caspase-3 and cleaved PARP-1 in hepatocytes appeared to be dependent on the presence of RUNX1 in the cocultured cancer cells." (PMID 35267627, 2022). "Poly (ADP-ribose) polymerase 1 (PARP1) participates in DNA damage repair in cancer cells." (PMID 35814435, 2022). "Thus PARP1 is up-regulated in cancers and inhibition of PARP1 and other PARPs is currently one therapeutic strategy." (PMID 36286592, 2022). "However, the synthetic lethal pair of BRCA1, the poly (ADP-ribose) polymerase 1 (PARP1) gene, has been shown as conserved in mostly BRAC1 mutated (BRCA1m) cancer cells and seems to be a promising pathway in sensitizing these cells to chemotherapy." (PMID 35879772, 2022). "Inhibition of DNA repair in cancer cells exposed to the test compounds may result from their interaction with the PARP1 protein and its degradation." (PMID 35682740, 2022). "In addition, they also caused inactivation of PARP1 by binding to its catalytic site wherein Olaparib (an established anti-PARP1 drug has been crystallized) binds resulting in the growth arrest/apoptosis in cancer cells." (PMID 36172283, 2022). "Recently, our laboratory and others showed that either Olaparib or PARP1 gene silencing activated STAT3 by increasing STAT3 phosphorylation through dePARylation in cancer cells and immune cells, partially counteracting the tumor cell-killing efficacy of Olaparib." (PMID 36324587, 2022).
cancer (continued). "Finally, anti-cancer drug olaparib strongly inhibits PARP1-dependent transcription through a nucleosome." (PMID 35806109, 2022). "Specific genetic deletion of PARP-1 and PARP-2 in lung cachectic mice prevented the loss of muscle mass and function through several mechanisms such as attenuation of muscle proteolysis, oxidative stress, and epigenetics in cancer-cachectic mice." (PMID 35740560, 2022). "PARP1 plays a role in cell apoptosis and is considered as a therapeutic target of certain cancers." (PMID 36257929, 2022). "The PARP1 inhibitors have been exploited clinically for the treatment of various cancers." (PMID 36299259, 2022). "PARP1 has been explored to influence immune components in some types of cancers, which may also explain the higher proportion of inflamed immune subtypes in low-risk CC patient populations." (PMID 36091054, 2022). "Therefore, PARP-1 inhibition is cytotoxic for cancer cells and is used both as a cancer monotherapy or in combination with chemotherapy." (PMID 35158955, 2022). "Despite the well-known tumourigenic role of PARP-1 that places it as an appealing therapeutic target, the mechanisms underlying its specific function in cancer have not yet been fully elucidated." (PMID 35158955, 2022). "The expression levels of both cleaved caspase-3 and cleaved PARP-1 were significantly increased in the cocultured hepatocytes compared to control, specifically, in the hepatocytes that were in direct contact with cancer cells." (PMID 35267627, 2022). "Increased DNA replication stress in cancer cells could lead to an upregulation of pathways that stabilize replication forks, and at the same time, might increase the dependency of these cancer cells on PARP1." (PMID 36350633, 2022). "Additionally, the correlation analysis from the same TCGA pan-cancer data showed that PARP1 expression strongly correlated with AKT1 expression." (PMID 36203459, 2022). "PARP1 inhibitors have been approved for treating cancer patients." (PMID 34935305, 2022). "It is indicated that the inhibitors with contacts with HD could trap PARP-1 on DNA damage and show enhanced killing ability against cancer cells." (PMID 36353483, 2022). "PARP1 overexpression has been demonstrated in many cancers, which indicates its importance in cancerogenesis and may be an independent prognostic factor." (PMID 36533080, 2022). "PARP1 has implications not only in cancer but also in neurodegenerative diseases; activation of PARP1 has been linked to PD pathogenesis in a mouse model, and changes in PAR polymers present in cerebrospinal fluid and brain homogenates of PD patients have been reported." (PMID 35741059, 2022). "In addition, significantly increased expression of PARP1 and PARylation have been detected in malignant tumors of various cancer types." (PMID 36284291, 2022). "Thus, PARP1 has been considered as a pharmacological target for the treatment of cancers that have DNA repair defects." (PMID 36172283, 2022). "Overexpression of mortalin and PARP1 has been shown to promote migration of cancer cells." (PMID 36172283, 2022). "MUS81 defects sensitize cells to various genotoxic chemicals, and it was recently shown that inhibition of MUS81 sensitizes HR-proficient cancer cells to the PARP1 inhibitor, olaparib, an agent commonly used to treat cancers with HR defects, such as BRCA1- and BRCA2-defective breast cancers." (PMID 36203968, 2022). "The molecular action mode of PARP1 in gene transcription may present as a potential target for therapeutic intervention of inflammation-related diseases and also for cancer therapy." (PMID 36077699, 2022). "The combined effect of PARP1 inhibitor and platinum drugs is expected to be effective in curing the disease; because when the damages are accumulated and the DNA repair is prevented, cancer cells are doomed to death." (PMID 35501851, 2022).
cancer (continued). "In other words, C12orf48 might have an important bearing on the protection of cancer cells from apoptosis under the circumstances of DNA damage or cellular stresses on the basis of its positive regulation towards PARP1 activity." (PMID 35100974, 2022). "The nucleoplasm node also contained some well-known cancer-related proteins, such as PARP1." (PMID 35626021, 2022). "PARP1 or PARylation also participate in the transcription regulation of many other genes and cellular processes, such as in fat production, cardiovascular and cancer formation." (PMID 36077699, 2022). "The DNA repair activity of PARP1 has been targeted in combination with radiotherapy based on the finding that inhibition of PARP1 may increase the radiosensitivity in cancer cells." (PMID 36230796, 2022). "Screening PARP-1 inhibitors with potential allosteric mechanisms and induced autophagy process could achieve elevated potency toward cancer cell killing." (PMID 36353483, 2022). "Particularly, previous studies showed PARP1 regulated in cancers by inducing cell apoptosis." (PMID 36257929, 2022). "In addition, PARP-1 strongly contributes to chronic inflammation and genomic instability, two hallmarks of cancer." (PMID 35158955, 2022). "Thus, PARP1 participates in the occurrence and development of cancer through complex regulatory mechanisms." (PMID 36566215, 2022). "Since PARP-1 is primarily involved in the DNA repair process, the authors of this study combined EV therapy with cisplatin, which induces DNA damage, and found that decreased expression of PARP-1 enhanced the chemosensitivity of cancer cells to cisplatin, showing synergistic cytotoxicity." (PMID 36297672, 2022). "Indeed, our results suggested a significant increase in the expression levels of cleaved caspase-3 and cleaved PARP-1 in hepatocytes that were neighbouring cancer cells in vessel co-opting RHGP lesions." (PMID 35267627, 2022). "PARP-1 is an important clinical target in the treatment of cancer." (PMID 36323657, 2022). "In summary, the degrader 206 (iRucaparib-AP6), by blocking both the catalytic and scaffolding functions of PARP1 without causing PARP1 trapping, provided an ideal approach for the treatment of cancers and other diseases caused by PARP1 hyperactivation." (PMID 35680848, 2022). "To date, PARP-1 inhibitors have been approved for the treatment of several types of cancer patients, and PARP inhibitors might be an innovative approach to the treatment of inflammatory disorders and neurodegenerative diseases." (PMID 35098371, 2022). "In this study we seek to deliver alpha-radiation directly to cancer cell nuclei by targeting PARP1." (PMID 36396952, 2022). "Moreover, in agreement with previous data showing that oxidative stress induces PARP1 activation, we found that the PARP1 gene was overexpressed in cancer patients." (PMID 35740268, 2022). "Unlike normal cells, BRCA1/2-deficient cancer cells critically depend on PARP1 for backup DNA repair leading to selective killing of these cancer cells by targeting PARP1 and recent regulatory approval of several PARP1 inhibitors (PARPis) for BRCA1/2-linked OC." (PMID 36183837, 2022). "As YHP-836 showed enzymatic inhibitory activity against PARP1 and PARP2, we investigated if YHP-836 could suppress cancer cell proliferation with BRCA mutations via synthetic lethality." (PMID 35910366, 2022). "PARP1 is thought to aid cancer progression by promoting cell proliferation in OSCC." (PMID 34440228, 2021). "PARP-1 has been long involved in cancer development and inflammation." (PMID 34567413, 2021). "CSN5 has been reported to participate in cancer cell death, but we couldn’t determine the alteration of cleaved PARP1 in both Siha and Hela cells in CSN5-depleted cells." (PMID 34247597, 2021).
cancer (continued). "Based on our data, we propose that inhibitors should be tailored to the PARP1 – HPF1 pair instead of just PARP1 and may result in higher selectivity for inhibition of PARP1 in the DNA-damage response, and thus for cancer treatment." (PMID 33531508, 2021). "PARP1 is overexpressed in many cancers and correlated with poor prognosis." (PMID 34880209, 2021). "PARP1 is mainly involved in DNA damage repair and is overexpressed in cancer stem cells." (PMID 34295821, 2021). "Additionally, TDP1 has been suggested as a promising target in the treatment of HPV-induced cancers, where it, along with PARP1, has been shown to be essential for the initial amplification of the high-risk HPV genome." (PMID 34300575, 2021). "PARP1 emerged as an attractive target for cancer therapy as it is involved in DNA repair processes." (PMID 34445442, 2021). "It will be of great interest to examine this radiotracer and radiolabeled bromo- and iodo-derivatives and test these PARP-1 radiotracers in different PARP-1-enriched cancer models to develop more potent radiotracers with favorable in vivo properties, using talazoparib as a leading scaffold." (PMID 34069967, 2021). "For this aim, we tested the effect of chaetocin on 53BP1 foci induced by doxorubicin, which targets topoisomerase II, or olaparib, a specific PARP1 inhibitor that is used in cancer treatment by itself or in combination with other drugs as a form of synthetic lethality." (PMID 34540832, 2021). "Therefore, it has been demonstrated that PARP-1 accomplishes multiple roles in transcriptional regulation in cancer cells, including properties closely related to genome maintenance, such as DNA repair." (PMID 33805293, 2021). "Inhibition of PARP-1 is an emerging therapeutic target in cancer therapy, thus its activation by the reduction in cellular nicotinamide levels by NNMT may contribute to the pro-oncogenic effect of PARP-1." (PMID 34680055, 2021). "Other authors also noticed that TDP1 together with PARP1 inhibition could be a successful cancer treatment strategy." (PMID 34768766, 2021). "Yet, further investigations are needed to reveal whether PARP-1-dependent effects on glycolytic activity of irradiated cancer cells are also due to inhibition of HK-1." (PMID 34825138, 2021). "The role of BER in cancer drug resistance had been proposed by many studies, and PARP1 plays an important role in the BER pathway." (PMID 34497808, 2021). "The role of PARP1 in cancer cell autophagy is somewhat controversial." (PMID 33922595, 2021). "Consequently, as was revealed, the more sensitive a cancer cell line to the cytostatic and cytotoxic effects of a tested compound, the higher the increase of the relative PARP1/ACTB and PARP2/ACTB mRNA ratios observed." (PMID 34440232, 2021). "The PARP1-inhibitor olaparib is used in the clinic to treat different types of cancer." (PMID 33926008, 2021). "Various cancers were shown to respond well to PARP1/2/3 inhibitors (PARPi)." (PMID 34639169, 2021). "Moreover, along with the knockdown of LINC00152, PARP1 expression was significantly decreased, which in turn increased the sensitivity of cancer cells to the DNA damaging agent doxorubicin." (PMID 34295821, 2021). "Thus, the interplay between PARP1 and pRb is multidimensional and covers not only the regulation of cancer cell proliferation, but also the sensitivity to chemotherapeutics and, theoretically, also to radiation." (PMID 33922595, 2021). "The authors also noticed that TDP1 and PARP1 inhibitors might also be effective against HPV-induced cancer." (PMID 34768766, 2021). "Caspase-3 may be responsible for PARP-1 cleavage in cancer cells, resulting in the increase in 89 kDa and 24 kDa fragments." (PMID 33578817, 2021). "These promiscuous effects on both normal and cancer cells could have resulted from the competitive nature of NAD-like PARP-1 inhibitors olaparib and rucaparib." (PMID 34638458, 2021).